RIPK3 (receptor interacting serine/threonine kinase 3)
Diseases named in the same sentence as RIPK3 in open-access papers (continued):
Sharing a sentence is not in itself a finding about the gene and the disease.
cancer (continued). "RIPK3 can assist cancer cells in evading immune surveillance by promoting the aggregation of MDSCs and TAMs." (PMID 38684668, 2024). "Definitive evidence has shown that inducing RIPK1/ RIPK3-mediated necroptosis has the ability to eliminate cancer cells that have acquired resistance to apoptosis." (PMID 38553639, 2024). "The RIPK3 safety switch synergistically enhances the therapeutic efficiency of cancer cell–based immunotherapy and promotes long-term immunity." (PMID 39560995, 2024). "Regarding DNA methylation of the RIPK3 locus, the three annotated CpG probes were increasingly (significantly) methylated from normal tissues to primary tumors and to cancer cell lines." (PMID 38397165, 2024). "Previous studies indicated that the role of RIPK3 in cancer cell survival and death is context-dependent." (PMID 39540935, 2024). "In several breast cancer cell strains, knocking down RIPK1, RIPK3 or MLKL genes in cancer cells greatly lowered their tumorigenicity." (PMID 37744268, 2023). "The results showed that MLKL had a strong positive correlation with CASP8, ZBP1, FASLG, RIPK1, and RIPK3 in all 33 cancer types, and RIPK3 was also strongly correlated with CASP8, MLKL, and ZBP1." (PMID 37000317, 2023). "The absence or epigenetic silencing of RIPK3 expression via hypermethylation has been documented to inhibit necroptosis in various cancers, such as lung, gastric, ovarian, and colorectal cancer." (PMID 37612409, 2023). "For instance, FADD, FASLG, RIPK1, RIPK3, and TNF were more prone to copy number gain than loss in pan-cancer, but FAS and TLR3 displayed the reverse tendency." (PMID 37351504, 2023). "RIPK1 is highly expressed in KIRC and is upregulated by TNF-α, which further induces necrotic apoptosis of cancer cells through the RIPK1/RIPK3/MLKL/Drp1 axis." (PMID 37847185, 2023). "USP22 accelerates necroptotic cell death in several cancer cells via regulating RIPK3 ubiquitination." (PMID 36906615, 2023). "Previous studies have shown that many cancer cells inhibit necroptosis through epigenetic silencing of RIPK3." (PMID 37744268, 2023). "The activation of RIPK3 resulted in the inhibition of TRIM28 in cancer cells and the enhancement of the antitumor microenvironment." (PMID 36849530, 2023). "On the other hand, the expression of RIPK3 showed a positive correlation with most immune checkpoints, only in nine cancer types such as KIRC, KIRP, PRAD, SARC, SKCM, and TCGT." (PMID 37000317, 2023). "DNA (-cytosine-5)-methyltransferase 1 (DNMT1) has been reported for silencing TNFα-RAPK1 and RIPK3-mediated necroptosis in cancer cell lines through hypermethylation." (PMID 36349193, 2022). "In a panel of more than 60 cancer cell lines, two-thirds of the cells had reduced levels of the RIPK3 protein, and cancer cells tended to escape necrosis to survive." (PMID 36544770, 2022). "The reduced expression of RIPK3 and MLKL is associated with worse prognosis and poor survival in these cancers." (PMID 39872161, 2022). "Ungeremine, an alkaloid derivative, has been shown to overcome drug resistance in many cancer cells through escalating RIPK3-mediated necroptosis." (PMID 36361505, 2022). "Multiple cancers suppress necroptosis through epigenetic silencing of RIPK3, which is consistent with our obtained finding that the mRNA expression of RIPK3 in the model is negatively correlated with the patient’s risk score." (PMID 36506314, 2022). "Through differential expression analysis, we found that MLKL was highly expressed in CRC tissues, while RIPK1 and RIPK3 were lowly expressed in cancer tissues." (PMID 36544770, 2022). "Little is known about MLKL, the executioner activated by RIPK3 during necroptosis, and its opposing roles in cancer." (PMID 35422482, 2022). "In summary, our results demonstrated that IDOAMP inhibited Aurora kinase A, promoting the RIPK1/RIPK3/MLKL necrosome activation to antiprostate cancer." (PMID 35965682, 2022).
cancer (continued). "Among them, MLKL was highly expressed in cancer tissues, while RIPK1 and RIPK3 were lowly expressed in cancer tissues." (PMID 36544770, 2022). "Downregulation of the gene expression of cell death regulators such as CASP8 and RIPK3 are well-known mechanisms that are exploited by cancer cells to evade cell death by apoptosis or by necroptosis, respectively." (PMID 35422482, 2022). "In comparison, FADD in 12 cancer types, FASLG in 3 cancer types, RIPK1 in 19 cancer types, TLR3 in 25 cancer types, TNF in 11 cancer types, FAS in 22 cancer types, MLKL in 15 cancer types, and RIPK3 in 12 cancer types had homozygous deletions." (PMID 35748782, 2022). "This RIPK3‐mediated regulatory axis serves in maintaining the homeostasis of the DP thymocytes population and can provide a potential therapeutic target in cancer patients." (PMID 36161785, 2022). "The expression of HSP90α, HIF1α and RIPK1 was stronger in cancer tissues than in liver tissues; however, RIPK3 was expressed more in liver tissues." (PMID 33440739, 2021). "In contrast, RIPK3-expressing cancer cells undergo a type of caspase-independent programmed cell death, necroptosis, upon death-ligand stimulation." (PMID 34158609, 2021). "We found that, in most cases, the expression of RIPK3 in cancer tissues was lower than that in normal tissues, and there are still about 25% cases showing the opposite situation." (PMID 33440739, 2021). "Strategies that elevated RIPK3 expression were required since losses of RIPK3 expression exists in many types of cancer and genotypes of ICD cells largely restrict their immunogenicity." (PMID 34135914, 2021). "It is already known that most cancer cells lose RIPK3 expression, so the downregulation or deletion of RIPK3 during tumorigenesis accompanied by necroptosis resistance determines a poor prognosis." (PMID 33567618, 2021). "The levels of the RIPK3 protein were decreased in two thirds of a cohort of more than 60 cancer cell lines, suggesting that cancer cells prefer to evade necroptosis for survival." (PMID 32778143, 2020). "In line with the findings of several studies, RIPK3 expression is silent in a majority of cancer cell lines." (PMID 31914150, 2020). "These two death pathways were activated in VPS4A+B‐depleted CRC cells that cannot undergo classical necroptosis, due to the downregulation of RIPK3 (typical for many cancer types)." (PMID 31930723, 2020). "Specificity protein 1 (Sp1), a zinc-finger transcription factor, directly regulates RIPK3 expression in cancer cells." (PMID 31719524, 2019). "Inhibiting RIPK1 with Nec-1 or downregulating of RIPK3 abrogated edelfosine-induced cell death and increased cancer cell viability." (PMID 31766571, 2019). "Overall, these observations strongly suggest that pathways downstream of BRAF and AXL are responsible for RIPK3 expression suppression and escape from necroptosis in cancer." (PMID 30157175, 2018). "Our results suggest that therapies targeting key oncogenes BRAF and AXL result in a regain of RIPK3 expression in cancers that have lost it." (PMID 30157175, 2018). "RIPK3 expression is repressed in several types of cancers and cancer cell lines, which results in the inhibition of necroptosis." (PMID 30158588, 2018). "Prophylactic immunization of mice with cancer cells that are dying by necroptosis induced by conditional activation of a RIPK3 transgene construct can induce antitumor immunity." (PMID 30143632, 2018). "Although further investigations are needed to define the role of necroptosis in cancer, inducing RIPK-3 dependent necrosis is an attractive strategy to circumvent apoptosis resistance from chemotherapeutic or targeted agents on cancer cells." (PMID 28613269, 2017). "In many cancer cell lines, the expression of RIPK3 is lost due to genomic methylation near its transcriptional start site." (PMID 27920775, 2016). "RIPK3 silencing in cancer cells was reported to suppress the complex regulation of the apoptosis/necroptosis switch and NF-κB activation." (PMID 27429198, 2016).
cancer (continued). "RIPK3 expression is likely repressed during cancer development or progression, by methylation of the genomic region near its transcriptional start site." (PMID 27429198, 2016). "To further address the role of RIPK3 in chemotherapeutic agent-induced cell death, we stably expressed RIPK3 in the RIPK3-negative cancer cell lines HCT116, SW480, and MDA-MB-231." (PMID 25675296, 2015). "Immunohistochemical analysis confirmed that RIPK1 and RIPK3 were expressed in colonic enterocytes and lamina propria mononuclear cells in normal tissue, and that their expression was reduced in cancer tissues." (PMID 25675296, 2015). "Necroptosis, IL-1α release, and enhancement of DC activation were dependent on the expression of RIPK3 in cancer cells." (PMID 25888634, 2015). "Alternatively, pathway-specific drugs that enhance RIPK3 expression and more potently induce necroptotic cell death will be needed to fully harness the power of necroptosis in anti-cancer therapy." (PMID 25675296, 2015). "The roles of RIPK3 in cancer, in many cases, seem paradoxical." (PMID 40010643, 2025). "The inhibitory effect of Phen on TNF-mediated necroptosis was also evident in another human cancer cell line, an ectopic RIPK3-expressing MDA-MB231 cell line, as well as in murine MC-38 cells and MEFs, expanding this observation to multiple cell types and species." (PMID 40456737, 2025). "However, in vitro necroptosis assays are limited by the fact that many cancer cell lines show epigenetic silencing of RIPK3 under artificial in vitro culture conditions." (PMID 40345706, 2025). "Finally, the role of the balance between RIPK1 and RIPK3 in inducing cell death in cancer cells has recently been highlighted by the study using Protac targeting RIPK1, which was able to induce cell death in cancer cells." (PMID 40240880, 2025). "In contrast to its immunogenic counterpart MOC1, the poorly immunogenic carcinoma cell line MOC2 showed little expression of RIPK3 and consequently no susceptibility to TSZ-induced necroptotic cell death in vitro." (PMID 40345706, 2025). "RIPK3 inhibitors can be used to suppress the occurrence and development of these cancers." (PMID 38684668, 2024). "In early cancer detection, the hypermethylation status of RIPK3, along with other biomarkers, could be used as a precision medicine." (PMID 38397165, 2024). "In this study, we repurposed and characterized a dual-function, inducible RIPK3-driven necroptotic suicide system that functions as a safety switch and can synergistically boost the efficiency of cancer cell–based immunotherapy, which in turn induces long-term immunity that prevents recurrence." (PMID 39560995, 2024). "This increased destabilization of RIPK3 could prevent necroptotic cell death when apoptosis is suppressed, leading to chemoresistance against anti-cancer drugs." (PMID 39540935, 2024). "However, existing studies suggest that RIPK3 has contradictory effects on cancer based on the type and specific development stage of cancer." (PMID 38684668, 2024). "Even though in vitro research indicates that invasive cancer cells lack RIPK3 expression, the biological function of RIPK3 in a situation pertinent to the disease is still unknown." (PMID 39118979, 2024). "In numerous cancer types, a downregulation of key molecules involved in necroptotic signaling pathways, such as RIPK3, has been identified, suggesting that cancer cells may evade necroptosis." (PMID 38994937, 2024). "Decreased RIPK3 expression has been reported in several types of cancer patients’ samples." (PMID 38799433, 2024). "To determine whether ZBP1-derived PANoptosome assembly was triggered by chemotherapy in cancer patients, we performed PLA assay in colonic tissues to examine the association between ZBP1 and RIPK3 or Casp-6, respectively." (PMID 39465258, 2024). "RIPK3 has been shown to be epigenetically silenced in many cancers." (PMID 38893185, 2024).
cancer (continued). "The PIM2- and ERK2-mediated phosphorylation of RIPK3 at its degron motifs may be a key signaling pathway determining whether cancer cells survive or undergo necroptotic death." (PMID 39540935, 2024). "Additionally, prunetin (PRU), an O-methylated flavonoid, can be used to treat gastric cancer, as it can inhibit cancer cell proliferation through necroptosis by activating RIPK3 and phosphorylating MLKL." (PMID 38684668, 2024). "Its expression can be silenced by methylation in cancer cell lines, potentially allowing tumor cells to avoid treatment regimens, while others have speculated a role for RIPK3 in controlling cancer development and progression." (PMID 39768199, 2024). "Targeting RIPK3 may be beneficial in diseases where RIPK3‐mediated necroptosis plays a critical role, such as certain types of cancer and inflammatory conditions." (PMID 39239068, 2024). "Moreover, TSC1/mTOR was found to control RIPK3-dependent necroptosis in intestinal inflammation and cancer." (PMID 38161978, 2023). "The reduced expression of RIPK3 and resistance to necroptosis resulting from epigenetic and genetic changes may benefit the survival of cancer cells." (PMID 36849530, 2023). "In addition to this, RIPK3 can induce the production of cytokines to activate natural killer T cells, which also help to kill cancer cells." (PMID 36506314, 2022). "Survival analysis showed that CNVs of TNF in 22 cancer types, TLR3 in 10 cancer types, RIPK1 in 9 cancer types, FAS in 8 cancer types, FADD in 8 cancer types, RIPK3 in 7 cancer types, MLKL in 6 cancer types, and FASLG in 5 cancer types were significantly associated with overall prognosis." (PMID 35748782, 2022). "Meanwhile, homozygous CNV analysis showed that FADD in 22 cancer types, FASLG in 25 cancer types, RIPK1 in 22 cancer types, TLR3 in 15 cancer types, TNF in 23 cancer types, FAS in 15 cancer types, MLKL in 12 cancer types, and RIPK3 in 17 cancer types had homozygous amplifications." (PMID 35748782, 2022). "Importantly, a study evaluating transcriptome analysis of 941 cancer cell lines found that high AXL mRNA levels indicate resistance to necroptosis while low RIPK3 mRNA levels predict resistance to necroptosis." (PMID 36186479, 2022). "In contrast, low or undetectable expression of RIPK3 is witnessed in numerous cancer cell lines." (PMID 36292722, 2022). "Among them, the synergy with ferroptosis, further RIPK1/RIPK3/MLKL studies, its association with inflammation and oxidative stress and translational applications, and the therapeutic potential to treat cancer and neurodegenerative diseases are the trending research area." (PMID 35769473, 2022). "On the other hand, aggressive induction of apoptosis or pyroptosis by RIPK3 inhibitors HG-9-91-01 we revealed here may have specific utility in cancer chemotherapy." (PMID 35217652, 2022). "Another study showed that the activation of RIPK3 results in a reliable derepression of tripartite motif-containing 28 in cancer cells, thereby inducing increased production of immunostimulatory cytokines in the tumor microenvironment (TME), thus promoting potent cytotoxic antitumor immunity." (PMID 36159818, 2022). "RIPK1 and RIPK3 are activators of necroptotic cell death, which has been shown to exert complex functions in diverse disease states, including infection, cancer, and sterile injury." (PMID 34333522, 2021). "Similarly, TNF-driven necroptosis in cancer cells can propagate RIPK3-dependent immunosuppression by ablating the release of pro-inflammatory factors, despite proficiently releasing various DAMPs." (PMID 32752206, 2020). "Many cancer cells exert a defect in necroptosis due to epigenetic silence of Ripk3 gene." (PMID 32411707, 2020). "Moreover, RIPK3, highly expressed in mouse models of CRC and in a subset of human CRC cell lines, seems to be the deciding factor of cancer cell susceptibility, second to mitochondria-derived activator of caspase (SMAC) mimetic-induced necroptosis." (PMID 33050394, 2020).
cancer (continued). "Necroptosis is a different way of killing cancer cells: this version of caspase-independent cell death is characterized by receptor-interacting protein kinase-3 (RIPK3) and mixed lineage kinase-like domain protein (MLKL) activation, leading to cell membrane rupture and controlled cell lysis." (PMID 32826875, 2020). "Interestingly, genome-wide analysis identified that such DNA methylation-driven suppression of RIPK3 levels was oncogene-enforced and accordingly facilitated cancer cells’ ability to avoid necroptosis." (PMID 32752206, 2020). "Indeed, previous studies have reported that B-RAF inhibitors, such as dabrafenib, vemurafenib, and sorafenib, that are FDA-approved anti-cancer drugs, can block RIPK3." (PMID 31817643, 2019). "The study has indicated that the ubiquitin-proteasome system may be a potential regulatory pathway for RIPK3-dependent necroptosis and that proteasome inhibitors can be developed as an anti-cancer agent targeting necroptotic pathway." (PMID 31122251, 2019). "The delineation of the exact mechanistic details downstream of BRAF/AXL and upstream of transcription factors that control RIPK3 transcription is likely to be of importance to our understanding of cancer escape from necroptosis and will be elucidated in future studies." (PMID 30157175, 2018). "In cancer cells, RIPK3 interacts with and phosphorylates MLKL to promote necroptosis." (PMID 30005626, 2018). "An increasing number of studies have demonstrated that downregulation or mutations of necroptosis regulators including RIPK1, RIPK3, MLKL and CYLD are frequently found in human tumors, which indicates the pivotal roles of necroptosis in the pathogenesis of cancer." (PMID 30005626, 2018). "Furthermore, the RIPK3 gene is located on chromosome 14q11.2, a locus frequently altered in many cancers including nasopharyngeal carcinoma and T cell leukemia/lymphoma." (PMID 27429198, 2016). "Therefore, we next addressed whether cancer immunotherapy with ICI also relies on the activity of RIPK3 as a component of the necroptosis pathway upstream of MLKL." (PMID 40345706, 2025). "In accordance with these observations, the analysis of the mRNA expression levels of RIPK1 and RIPK3 using The Cancer Genome Atlas (TCGA) database revealed that the mRNA of RIPK1 has significantly higher expression levels than the one of RIPK3 in most cancer tissues (Fig. EV3G)." (PMID 40240880, 2025). "Due to its involvement in necroptosis, RIPK3 may play a role in cancer development." (PMID 40508046, 2025). "This may be the most important reason for RIPK3 silencing in cancer." (PMID 40010643, 2025). "At low doses, these complexes are highly cytotoxic for cancer cells inducing a significant loss of cell viability that is partially decreased by Z-VAD (apoptosis inhibitor), but also by Nec-1 (RIPK1 inhibitor) and GSK872 (RIPK3 inhibitor), suggesting that both cell death routines are activated." (PMID 38806468, 2024). "Additionally, RIPK3 expression is decreased in malignancies in IBD patients, which subsequently demonstrates that RIPK3 expression is downregulated in human CRC and is associated with the development of cancer." (PMID 39118979, 2024). "Therefore, a mechanism whereby SPOP-mediated RIPK3 regulation may sensitize cancer cells to death through SPOP modulation was proposed." (PMID 39540935, 2024). "However, whether RIPK3 plays a pro- or anti-cancer role primarily depends on the relative quantity of the released chemokines and cytokines." (PMID 38684668, 2024). "Moreover, membrane depolarization is a crucial event in the activation of TRAIL, a ligand that causes fragmentation of mitochondria in multiple human cancer cell lines, ultimately inducing apoptosis and necroptosis by activating caspases and RIPK1/RIPK3, respectively." (PMID 37612409, 2023). "Regulation of RIPK3 levels could indeed be a mechanism relevant to inflammation and cancer." (PMID 36658119, 2023).